VEGFA (vascular endothelial growth factor A)
Diseases named in the same sentence as VEGFA in open-access papers (continued):
Sharing a sentence is not in itself a finding about the gene and the disease.
tumor (continued). "Specifically, SA binds to PHD2 and inhibits its activity, preventing its interaction with the ODD domain of HIF-1α, thereby enhancing HIF-1α stability and promoting tumor angiogenesis by upregulating VEGFA expression." (PMID 37906252, 2023). "Mouse xenograft transplantation assays was conducted to validate the obtained findings on the relationship between STK24 and STAT3/VEGFA signaling pathway in tumor angiogenesis." (PMID 36720310, 2023). "The inhibition of HIF-1α/VEGFA can successfully suppress tumor growth, metastasis, and angiogenesis." (PMID 37239383, 2023). "To summarize, our study shows that DHA significantly inhibits OS cells proliferation, migration, and invasion by suppressing the expression of LOXL2, a tumor-promoting factor, and reducing VEGFA expression by directly regulating LOXL2." (PMID 37056396, 2023). "Nevertheless, we observed that the concomitant BRAF inhibition counteracts the PMN‐MDSC tumor infiltration induced by anti‐m‐VEGFA treatment." (PMID 37183363, 2023). "Other negative regulators of antitumor immunity, like TGF-β and VEGFA, are also involved in immune escape of tumor cells and induce immunotherapy resistance." (PMID 37573354, 2023). "It is well known that high VEGFA and HIF-1α expression levels are associated with a worse outcome in a wide array of malignancies through promoting tumor angiogenesis." (PMID 36678795, 2023). "Cancer cells secrete VEGFA, which initiates tumor angiogenesis through binding to VEGF receptor 2 (VEGFR2) expressed on adjacent vascular ECs." (PMID 37046617, 2023). "In adipocytes, NLRC4 inflammasomes induce tumor infiltration into myeloid cells, and IL-1β promotes vascular endothelial growth factor A (VEGFA) secretion and angiogenesis, thereby driving disease progression." (PMID 37020871, 2023). "In particular, a high density of CD68+ TAM was associated with a higher density of micro-vessels and vascular endothelial growth factor A (VEGF-A), markers of vascular neovascularization and tumor remodeling." (PMID 37465638, 2023). "It is well established that EMT process is associated with tumour angiogenesis, and SLUG expressed in tumour cells promotes the angiogenesis through VEGFA and CXCL12 production." (PMID 37867401, 2023). "CRC cells with high expressions of miR-206 and miR-133b exhibited the downregulation of MMP2 and VEGFA protein levels, indicating a potential influence on the tumor microenvironment matrix." (PMID 38069061, 2023). "Other studies have shown that miR-145 inhibited tumor angiogenesis by targeting several pro-angiogenic genes, including VEGFA, EGFR and MMP2." (PMID 37108432, 2023). "This study established the differential expression of three key hypoxia genes, ANGPTL4, P4HA1, and VEGFA, which were correlated with several radiomic texture features, mainly focusing on tumour heterogeneity." (PMID 37048688, 2023). "On the other hand, activation of STAT3 signaling pathway promoted tumor progression and angiogenesis through the upregulation of VEGFA expression." (PMID 36720310, 2023). "The tumor then secretes pro-angiogenic signals including VEGFA to stimulate the formation of new blood vessels from existing vessels." (PMID 37508458, 2023). "Bevacizumab targets a protein called vascular endothelial growth factor-A (VEGF-A) and slows tumour growth and proliferation by preventing tumour angiogenesis, thereby depriving GBM cells of nutrient uptake." (PMID 38130720, 2023). "Among those, VEGFA guarantees both angiogenic switch and abnormal vasculature featured by vascular permeability, thereby favoring tumor intravasation and distant metastasis." (PMID 38274812, 2023). "Cancer cell-derived lactate leads to HIF-1α-dependent polarization of TAMs towards a tumor-permissive M2 phenotype and induces vascular endothelial growth factor A (VEGFA) expression in TAMs." (PMID 37490147, 2023).
tumor (continued). "Within panCK‐positive tissues high STAT3 within the stroma was associated with increased expression of VEGFA (p = 0.0110), which has been shown to be independently prognostic in TNBC and associated with more aggressive tumour phenotypes." (PMID 37199043, 2023). "Studies have also demonstrated that the FOXM1 transcription factor regulates VEGFA to promote tumor angiogenesis." (PMID 37081847, 2023). "Vascular endothelial growth factor A (VEGF-A) is well known to be the main molecular driver of tumor angiogenesis." (PMID 36928058, 2023). "Vascular endothelial growth factor-A (VEGFA) is a pro-angiogenic cytokine and a cell survival factor, which is well established as the primary factor driving an expansion of the tumour vascular bed." (PMID 38037065, 2023). "VEGFA (Vascular Endothelial Growth Factor A) is an important regulator of tumor angiogenesis in many solid tumors." (PMID 37328788, 2023). "In particular, IFN-γ released by NK cells is able to abrogate the angiogenic activity of tumor-associated neutrophils by suppressing vascular endothelial growth factor A (VEGF-A), thus restraining tumor growth." (PMID 37298470, 2023). "Preclinical studies have shown that tumor vascular modulation, driven by the concurrent targeting of VEGFA and ANGPT2, contributes to antitumor immunity through the activation and perivascular accumulation of T cells." (PMID 37843277, 2023). "IH increases the expression of hypoxia-vascular endothelial growth factor-A; subsequent angiogenesis can support tumor proliferation and metastasis." (PMID 38131038, 2023). "Multiple studies have shown that VEGFA expression is increased in various cancers and contributes to tumor progression at multiple levels, including proliferation, differentiation, and migration." (PMID 37592783, 2023). "VEGFA itself seems to act on tumor cells promoting the maintenance of an undifferentiated state, while its over-expression has already been related to CCSK." (PMID 36835166, 2023). "As a result, many studies have shown that ARL13B promotes angiogenesis and tumor growth by activating VEGFA–VEGFR2 signaling in glioma." (PMID 38201620, 2023). "First, animal experiments in vivo showed that separately silencing VEGFA or VEGFC significantly reduced the number of tumor cells in lymph nodes from the MFSD4A-AS1-overexpressing mice group." (PMID 36606578, 2023). "Immunohistochemistry results revealed that the Ki-67, OCT4, and VEGFA were inhibited by vitexin in tumour tissues (p < 0.01)." (PMID 36994813, 2023). "Towards this end, the VEGFA copy number, its expression in tumor tissues, and the density of tumor micro-vessels in mGC patient-derived samples were evaluated." (PMID 37893095, 2023). "VEGFA is involved in regulating the tumour microenvironment and immune cell function in tumour development." (PMID 36729917, 2023). "In tumor cells, the VEGFA-VEGFR2 binding activates autocrine survival and migration signaling in an angiogenesis-independent manner." (PMID 36874116, 2023). "VEGFA, has been widely recognized as a pro-angiogenic factor in vertebrates and a promoter of tumor progression for decades." (PMID 37138885, 2023). "Compared to control cells, CYP4Z1 overexpression in tumor cells increased the expression levels of vascular endothelial growth factor A (VEGF-A) and suppressed the expression levels of tissue inhibitors of metalloproteinases 2 (TIMP-2)." (PMID 38001897, 2023). "F4/80+ TAMs showed proximity to neovascularization and tumor vessels, functionally angiogenic in vivo; and greatly promoted the activation of a few key angiogenic markers such as VEGFA, Ki67, etc. in endothelial cells in vitro." (PMID 36781833, 2023). "The current study also investigated if STK24 regulates the secretion of VEGFA by cancer cells because VEGFA is an essential factor of tumor angiogenesis." (PMID 36720310, 2023).
tumor (continued). "The interaction between tumor cells and monocyte-macrophages (mo-Macs) is significant, especially for the activation of the growth factor signaling pathways VEGFA and VEGFB." (PMID 37187731, 2023). "HIF-1α and VEGFA are major regulators of tumor angiogenesis and of tumor progression in many types of cancer." (PMID 36678795, 2023). "High expression of VEGFA is positively correlated with hypoxia scores in most tumors, indicating a potential correlation with tumor aggressiveness." (PMID 37852616, 2023). "In B7H4 positive tumours, a cluster consisting of IL-5, IL-4, VEGFA, M-CSF, IFN-γ, IL-Ra, IL-8, and IL-1β was chosen for further analysis." (PMID 36980202, 2023). "LncRNA TUG1 was highly increased in ccRCC and acted as a ceRNA sponging miR-299-3p to induce the expression of VEGFA to promote tumor angiogenesis." (PMID 36732762, 2023). "Next, the relationship between VEGFA and tumour‐infiltrating immune cells (TIICs) was also revealed." (PMID 36729917, 2023). "Transwell invasion assays showed that miRNA-383-5p transfection reduced tumor cell invasiveness; however, tumor cell invasive functions were restored when miRNA-383-5p transfection and VEGFA overexpression occurred simultaneously." (PMID 37592783, 2023). "An altered status of VEGFA points to increased activation of downstream signal pathways involved in angiogenesis, tumor growth, and modulation of immune cells, resulting in greater responsiveness to the Ramucirumab." (PMID 37893095, 2023). "Focusing on tumor–stromal communication, the authors found that tumor cells expressing vascular endothelial growth factors (VEGFA and VEGFB) can stimulate a subpopulation of endothelial cells through VEGF receptors, FLT143 and beta-1 integrin." (PMID 37353907, 2023). "Given that tumor angiogenesis has been studied for decades, VEGFA clinical targeting led to several FDA-approved drugs." (PMID 36418472, 2023). "Activated NLRC4 inflammasomes from tumor-infiltrating myeloid cells produce IL-1β, which promotes vascular endothelial growth factor A (Vegfa) expression in adipocytes facilitating angiogenesis, a key step in metastasis." (PMID 36932407, 2023). "Recent clinical studies show that anti-VEGFA drugs can increase antitumor immunity in human cancers by modulating immune cell compositions and enhancing immune responses to the tumor." (PMID 38152616, 2023). "Defective STAT4‐induced lymphatic metastasis and immune suppression via increased lymph‐angiogenesis with elevated VEGFA expression and decreased production of IFN‐γ with CD4+ cell dependent in STAT4 deficient tumor bearing mice." (PMID 38107057, 2023). "Fascaplysin treatment also reduced the expression levels of cyclin D1, CDK4, Bcl-2 and VEGFA, demonstrating that fascaplysin showed anti-tumor activity on ovarian cancer cell lines by inhibiting CDK4." (PMID 37103365, 2023). "We first used the TIMER database to analyse the correlation of VEGFA expression with tumour purity and infiltration of six types of immune cells: CD8+ T cells, CD4+ T cells, B cells, dendritic cells, macrophages and neutrophils." (PMID 36729917, 2023). "VEGFA overexpression in the tumor represents mainly the response to increased tumor hypoxia via the hypoxia-inducible factor-1α (HIF-1α) pathway." (PMID 37893095, 2023). "TeMs also upregulated the expressions of VEGFA, implying a role for tissue macrophages in promoting tumor angiogenesis." (PMID 37488416, 2023). "In lung adenocarcinoma, the lncRNA LOC100132354 can affect the downstream target gene VEGFA to promote tumor angiogenesis." (PMID 37602326, 2023). "VEGFA plays a crucial role in tumor angiogenesis by binding to its specific receptor VEGFRs in endothelial cells." (PMID 36906615, 2023).
tumor (continued). "The study suggested that miR-4316 inhibited tumor proliferation and migration by repressing vascular endothelial growth factor A (VEGF-A)." (PMID 37177979, 2023). "We found a positive correlation between PD-L1 and VEGFA expression in the tumor cell lines including MDA-MB-231, LNCaP, MDA-MB-435, and DU145." (PMID 38152616, 2023). "HIFU ablation induced residual tumor angiogenesis by up-regulating HIF-2α/VEGFA/EphA2 pathway in HCC." (PMID 36814489, 2023). "The M2d sub-type, commonly referred to as tumor-associated macrophages (TAMs), promotes tumor progression by secreting TNFα, IL6, IL-10, TGFβ, and Vascular Endothelial Growth Factor A (VEGFA)." (PMID 37371552, 2023). "In contrast, the expression of VEGFA was up‐regulated within the transition track and was highest in the terminal state, indicating the terminally differentiated role of the pro‐tumour TAN‐2 subpopulation." (PMID 37491740, 2023). "MiR-29c also plays a tumor suppressor role in LUAD by directly binding to the 3′-UTR of vascular endothelial growth factor A (VEGFA) and repressing its expression." (PMID 37686110, 2023). "Gal-9 activate Tim-3 on macrophages and induce M2-like polarization and enhanced secretion of vascular endothelial growth factor A, resulting in tumor angiogenesis and tumor growth." (PMID 37598273, 2023). "The FRA-1-dependent control of VEGFA expression in invasive BCCs highlighted the FRA-1 participation in the VEGF-dependent tumor angiogenesis, which, in turn, contributes to the EMT-induced stemness resulting in the increased tumorigenicity of breast CSCs." (PMID 37176013, 2023). "Based on the key regulatory signals in the macrophage-tumor cell regulatory network, we performed a pseudotime analysis of the macrophages and found that signal molecules (TIMP1, VEGFA, SPP1) are highly expressed in immunosuppression-associated macrophages." (PMID 37189418, 2023). "Neural stem cells of glioblastoma promote angiogenesis by releasing VEGFA and differentiating into a tumor endothelial phenotype." (PMID 37508458, 2023). "There is known to be a direct relationship between VEGFA secretion by tumor cells and increased amounts of Treg at the tumor site." (PMID 37190304, 2023). "This demand is secured by an intense tumor-driven vascularization in which the vascular endothelial growth factor A (VEGF A) plays a crucial role." (PMID 36612306, 2023). "The molecular mechanisms suggested that TMTC3 facilitated tumor angiogenesis by regulating Rho GTPase/STAT3/VEGFA pathway mediated by interacting with IMPDH2 Bateman domain." (PMID 37752569, 2023). "By binding to vascular endothelial growth factor-A (VEGF-A), it blocks VEGF-A-induced angiogenesis, consequently inhibiting tumor metastasis and prolonging patients’ survival." (PMID 37547718, 2023). "VEGFA is a primary factor driving expansion of the tumor vascular bed and is produced by hypoxic tumor cells." (PMID 37123417, 2023). "We present the results of VEGFA‐negative and VEGFA‐positive expression in tumour tissue and peritumoral tissue, respectively." (PMID 36729917, 2023). "Intratumoral heterogeneity was validated in GBM-1, where regions 1–3 in close proximity have widely varied proportions of astrocytic and oligodendrocytic tumor phenotypes and significant alterations in gene expression in VEGFA, among others." (PMID 38077210, 2023). "Across tumor stages, VEGFA, VEGFC, and PGF exhibited an increasing expression tendency as the tumor stage advanced." (PMID 37852616, 2023). "Overexpression of lncRNA PVT1 activates the STAT3/VEGFA pathway, sparks the angiogenesis in tumor cells, and vigorously boosts GC progression in vitro and in vivo." (PMID 35012438, 2022). "VEGFA is one of the main factors driving tumor vascular bed expansion and is significantly upregulated in hypoxia." (PMID 36439446, 2022).
tumor (continued). "Subsequently, the data of western blotting showed that the protein levels of phosphorylated-JAK2, N-cadherin and VEGFA were reduced in tumor tissues exposed to oridonin, while E-cadherin protein level was elevated." (PMID 35813296, 2022). "For example, it has been demonstrated that primary tumour-secreted factors, such as the vascular endothelial growth factor A (VEGF-A) and placental growth factor (PGF), can mobilise hematopoietic cells in lungs before the arrival of metastatic cancer cells." (PMID 36612237, 2022). "We also found that Cancer Cells interact with ITGB1, highly expressed in multiple cells such as Fibroblasts, Endothelial Cells, and Basal Cells, through angiogenesis signal molecules (VEGFA) to stimulate tumor growth and metastasis." (PMID 36401283, 2022). "In contrast, tumor cells expressing VEGFA mRNA, along with nuclear HIF-1α, were found in adjacent, but not vascular, lesions." (PMID 35392912, 2022). "As a monoclonal antibody to vascular endothelial growth factor A, bevacizumab presents a therapy challenging this mechanism by reducing tumor angiogenesis, thus increasing proper perfusion, and lowering hypoxia and therefore radioresistance." (PMID 35503461, 2022). "We also predicted the interactions of nmTECs with vascular endothelial cells via VEGFA and VEGFE and with tumor-associated fibroblasts via PDGFA-PDGFRA." (PMID 35869073, 2022). "The miR-106a-5p miRNA is highly interconnected with the CD4+ T-cells regulation and works as a tumor suppressor by regulating the VEGFA gene." (PMID 36016137, 2022). "They promote tumor angiogenesis by secreting a variety of pro-angiogenic cytokines, including vascular endothelial growth factor A (VEGFA), platelet-derived growth factor β, angiogenin, placental growth factor, TGF-β, and matrix metalloproteinases (MMPs)." (PMID 35436935, 2022). "The expression levels of the Kdr gene encoding vascular endothelial growth factor receptor 2 (VEGFR2), the primary receptor of VEGFA, were similar between control and propranolol treated groups in all three tumor models tested." (PMID 35017664, 2022). "KDM4C was shown to promote tumor angiogenesis by transcriptionally activating the HIF1α/VEGFA signaling pathway." (PMID 35633893, 2022). "In this study, we found for the first time that PELP1 was positively correlated with MVD in CRC and proved that PELP1 regulated tumor angiogenesis through the STAT3/VEGFA axis." (PMID 35053547, 2022). "Further, we identified the vascularization by detecting the expression of vascular endothelial growth factor A (VEGFA) in the tumor microenvironment." (PMID 36359248, 2022). "VEGFA stimulates the proliferation of endothelial cells, forming a structurally abnormal and leaky tumor vasculature (Baluk, Hashizume, & McDonald, 2005; Ferrara, 2021; Jain, 2003, 2005; Nagy, Chang, Dvorak, & Dvorak, 2009)." (PMID 35577211, 2022). "Further validation of the cross-talk between GSK3α expression and regulation of the HIF1/VEGFA signaling pathway, both in vivo and in vitro, revealed that GSK3α-mediated cancer tumor angiogenesis was dependent on HIF1α expression in vitro." (PMID 35292059, 2022). "We next examined VEGFA, which is overexpressed and promotes tumor survival, growth, and metastasis in a range of human cancers." (PMID 36555662, 2022). "ICAM-1 and VCAM-1 have been found to be deregulated in tumor EC, possibly due to the high expression of VEGFA." (PMID 35216427, 2022). "Among them, TGFB1 and VEGFA are tumor-secreted immunosuppressive factors, while CD274 (PDL1) and PDCD1LG2 are both PD1 ligands and cell-surface immunosuppressive factors." (PMID 35222383, 2022). "Here, we reported for the first time that MIIP represses tumor angiogenesis by inhibiting production of VEGFA in TNBC cells." (PMID 36130933, 2022). "The formation of a dense ECM is closely related to the secretion of various factors (collagens I, III, IV, and V, as well as VEGFA, EGF, FGF, HGF, and CXCL12) by tumor-associated fibroblasts in tumor tissue." (PMID 35566065, 2022).